C5orf67 (chromosome 5 putative open reading frame 67)
Gene: Long non-coding RNA gene on chromosome 5 (56,493,622 to 56,670,173, reverse strand). Ensembl gene ENSG00000225940.
Diseases named in the same sentence as C5orf67 in open-access papers:
C5orf67 is named in the same sentence as 2 diseases in open-access papers, as found by Europe PMC text mining. Sharing a sentence is not in itself a finding about the gene and the disease. The quoted sentences say what the papers report.
Insulin resistance (1 paper, 2023). Increased resistance towards insulin, that is, diminished effectiveness of insulin in reducing blood glucose levels. "The remaining loci were associated with ISI, including 6 loci not previously implicated in post-challenge insulin resistance: MTOR, COBLL1, PPARG, C5orf67, FAM101A, SLC2A4." (PMID 37291194, 2023).
tumor (1 paper, 2024). "The long-range sequencing additionally showed that the normal, “empty” allele of C5orf67 without the HPV16 DNA insertion was also present in the tumor." (PMID 38898085, 2024).